CEP135 (centrosomal protein 135)
Description:
Centrosomal microtubule-binding protein involved in centriole biogenesis. Acts as a scaffolding protein during early centriole biogenesis. Required for the targeting of centriole satellite proteins to centrosomes such as of PCM1, SSX2IP and CEP290 and recruitment of WRAP73 to centrioles. Also required for centriole-centriole cohesion during interphase by acting as a platform protein for CEP250 at the centriole. Required for the recruitment of CEP295 to the proximal end of new-born centrioles at the centriolar microtubule wall during early S phase in a PLK4-dependent manner.
Synonyms: CEP4; KIAA0635; FLJ13621; MCPH8
Tractability: PROTAC: ubiquitination databases record sites on it; its protein half-life has been measured.
Gene: Protein-coding gene on chromosome 4 (55,948,819 to 56,033,361, forward strand). Ensembl gene ENSG00000174799.
Subcellular location: Cytoplasm, cytoskeleton, microtubule organizing center, centrosome, centriole
Subcellular location (Human Protein Atlas): Mid piece; Principal piece; Acrosome; Annulus
Pathways (Reactome):
Cell Cycle: AURKA Activation by TPX2; Loss of Nlp from mitotic centrosomes; Loss of proteins required for interphase microtubule organization from the centrosome; Recruitment of NuMA to mitotic centrosomes; Recruitment of mitotic centrosome proteins and complexes; Regulation of PLK1 Activity at G2/M Transition
Organelle biogenesis and maintenance: Anchoring of the basal body to the plasma membrane
Gene Ontology:
Molecular function: identical protein binding; microtubule binding; protein binding; protein homodimerization activity; tubulin binding
Biological process: centriole replication; centriole-centriole cohesion; positive regulation of establishment of protein localization; positive regulation of non-motile cilium assembly
Cellular component: centriole; centrosome; cytosol
Genetic constraint (gnomAD): Loss-of-function variants: 85 observed, 102.92 expected, observed/expected ratio (o/e) 0.83, 90% interval 0.69 to 0.99. The upper end of that interval is the gene's LOEUF score, 0.99, which puts it in group 4 of 6, group 1 being the genes least tolerant of losing a copy. Missense variants: 991 observed, 989.79 expected, observed/expected ratio (o/e) 1, 90% interval 0.95 to 1.05. Synonymous variants: 283 observed, 337.67 expected, observed/expected ratio (o/e) 0.84, 90% interval 0.76 to 0.93.
Homologues: Orthologues: chimpanzee CEP135 (99% identical), macaque CEP135 (98% identical), dog CEP135 (90% identical), rabbit CEP135 (90% identical), pig CEP135 (87% identical), guinea pig CEP135 (87% identical), mouse Cep135 (83% identical), rat Cep135 (82% identical), tropical clawed frog cep135 (60% identical). Paralogues in human: TSGA10 (23% identical), CROCC (20% identical), CEP250 (19% identical), CROCC2 (16% identical).
Diseases named in the same sentence as CEP135 in open-access papers:
CEP135 is named in the same sentence as 25 diseases in open-access papers, as found by Europe PMC text mining. Sharing a sentence is not in itself a finding about the gene and the disease. The quoted sentences say what the papers report.
microcephaly (6 papers, 2015 to 2025). A congenital or acquired developmental disorder in which the circumference of the head is smaller than normal for the person's age and sex. "However, molecular mechanisms for microcephaly mutations in centrosomal proteins, such as Cep135, Cep152, and WDR62, remain clouded." (PMID 38857398, 2024). "This is further supported by the fact that many genes associated with microcephaly encode centrosome proteins (CPAP, CEP152, CEP135, STIL, and CDK5RAP2) involved in centriole biogenesis and centrosome maturation." (PMID 39412222, 2025). "The same can be said for other genes such as CEP135 and PCNT which cause both non-syndromic and syndromic microcephaly." (PMID 36831309, 2023). "For instance, a study has recently grouped CEP135-mutated cases of MCPH and MOPD (microcephalic osteodysplastic primordial dwarfism) under the umbrella term of “CEP135 microcephaly”." (PMID 36831309, 2023). "Many genes have been implicated in the development of microcephaly (summarized inTable 1) includingASPM,MCPH1,CDK5RAP2,CEP152,CENPJ,WDR62,STIL,CASC5,CEP135,ZNF335,PHC1,CDK6, with many of them contributing to centrosome and spindle protein dysfunction during mitosis." (PMID 26535115, 2015).
infertile (3 papers, 2019 to 2022). "A previous report described an infertile patient carrying a homozygous variant (p.D455V) in CEP135 who showed the MMAF phenotype and for whom ICSI treatment was unsuccessful because of a lack of CEP135 in the PCs9." (PMID 35296684, 2022).
breast carcinoma (2 papers, 2020 to 2023). "As a necessary conserved central protein for centrosome replication, an imbalance of CEP135 results in centriole overduplication and contributes to chromosome segregation errors to promote breast cancer." (PMID 37051542, 2023).
glioma (2 papers, 2022 to 2026). A benign or malignant brain and spinal cord tumor that arises from glial cells (astrocytes, oligodendrocytes, ependymal cells). "Specifically, CEP135 was able to stratify patients with urothelial bladder carcinoma (BLCA), low-grade glioma (LGG), and sarcoma (SARC) cancers, with the most significant effect obtained in patients with LGG malignancies." (PMID 36435816, 2022).
brain cancer (1 paper, 2022). A primary or metastatic malignant neoplasm affecting the brain. "However, due to the difficulties in obtaining a tissue sample from brain cancers, CEP135 might be more suitable as a prognostic biomarker, rather than a predictive indicator of patients’ response to treatment." (PMID 36435816, 2022).
ciliopathy (1 paper, 2023). A genetic disorder of the cellular cilia or the cilia anchoring structures, the basal bodies, or of ciliary function. "In addition to the CPLANE genes, our search uncovered a number of additional ciliopathy genes associated with multi-systemic, brain, kidney, and eye ciliopathies (Cep135, Innp5e, Pex6, Togaram1)." (PMID 36737727, 2023).
DNA repair disease (1 paper, 2022). A disease that has its basis in the disruption of DNA repair. "CEP135 was identified as the most significantly perturbed gene among the studied DNA repair disorders and its expression correlates with the severity of survival of sarcoma patients where high expression of CEP135 is associated with poor survival probability." (PMID 36435816, 2022). "Our analysis revealed that CEP135, a scaffolding protein associated with early centriole biogenesis, is commonly downregulated in DNA repair diseases with high cancer predisposition." (PMID 36435816, 2022). "Notably, CEP135 was the most downregulated gene with a similar pattern of expression across the three DNA repair diseases, suggesting that it may be associated with the shared cancer phenotype." (PMID 36435816, 2022). "Thus, downregulation of CEP135 together with other identified hits may contribute to cell cycle dysregulation in DNA repair diseases." (PMID 36435816, 2022).
Intellectual disability (1 paper, 2021). "Biallelic single-bp deletions of the human CEP135 gene have been reported in MCPH patients with significant MCPH concomitant with severe intellectual disability and communication deficits." (PMID 34237032, 2021).
nasopharyngeal carcinoma (1 paper, 2023). A carcinoma arising from the nasopharyngeal epithelium. "The downstream target gene of hsa-miR-26b was identified as CEP135 by intersecting the predicted target genes from the TargetScan database with the target genes from the database of nasopharyngeal carcinoma mRNA data." (PMID 36820950, 2023). "Upregulation of CEP135 levels in nasopharyngeal cancer cell lines increased cell activity, accelerated cell migration, and inhibited apoptosis." (PMID 36820950, 2023). "MiR-26b downregulation leads to CEP135 overexpression and NF-κB pathway activation in NPC, which enhances proliferation, migration, and prevents apoptosis of nasopharyngeal carcinoma cells." (PMID 36820950, 2023).
sarcoma (1 paper, 2022). A usually aggressive malignant neoplasm of the soft tissue or bone. "Further screening of survival data in 33 cancers available at TCGA database identified sarcoma as a cancer type where lower survival was significantly associated with high CEP135 expression." (PMID 36435816, 2022). "Activation of PLK1 and upregulation of the PLK1-mediated signaling pathway in sarcoma patients could, therefore, be due to the high expression of CEP135, an associated upstream PLK1 regulator." (PMID 36435816, 2022). "The most significantly dysregulated gene CEP135 was further discovered to be used as a novel biomarker that stratifies sarcoma patients with better and poor survival outcomes among the TCGA database of 33 various cancer types." (PMID 36435816, 2022). "As such, we next aimed to analyze the group of sarcoma patients with high expression of CEP135 and lower survival outcomes in the context of target discovery." (PMID 36435816, 2022). "Out of five targets, only knockdown of PLK1 showed significant reduction in cell growth, posing PLK1 as a promising target for a subset of sarcoma patients with high CEP135 expression and poor survival rates." (PMID 36435816, 2022). "Collectively, these results highlight the importance of considering CEP135 as a novel marker gene for further investigations, since its association with sarcoma has not been well-characterized." (PMID 36435816, 2022). "CEP135 may, therefore, be potentially used as a predictive biomarker for sarcoma patients with poor survival, allowing the development of more tailored therapies for patients with unfavored clinical outcomes." (PMID 36435816, 2022). "Notably, levels of CEP135 in sarcoma significantly defined patients with high and low survival outcomes based on the obtained p-value." (PMID 36435816, 2022). "In this regard, CEP135 could be proposed as a novel predictive biomarker for sarcoma patient stratification." (PMID 36435816, 2022). "Stratification of cancer patients based on CEP135 expression enabled us to examine therapeutic targets that could be used for the improvement of existing therapies against sarcoma." (PMID 36435816, 2022). "Furthermore, using PandaOmics-based TargetID we revealed gene candidates that could be used as targets for drug discovery for more efficient elimination of cancer cells in sarcoma patients with high expression of CEP135 and lower survival probability." (PMID 36435816, 2022). "For novel target identification we have applied Pandaomics-based Target ID algorithm to compare differences between the transcriptomic data derived from sarcoma patients with low survival and high expression of CEP135 and non-tumorous tissue samples." (PMID 36435816, 2022). "Importantly, similar results have been obtained when comparison between two groups of sarcoma patients with high and low expression of CEP135 has been performed (data not shown)." (PMID 36435816, 2022).
tumor (7 papers, 2021 to 2026). "Taken together, our findings reveal a novel role for LZTS2 as a negative regulator of CEP135 and centrosomal microtubule nucleation, providing a potential mechanistic link to its tumor suppressor function." (PMID 40521914, 2025). "In conclusion, upregulation of CEP135 expression can further enhance proliferation and prevent apoptosis in tumor cells." (PMID 36820950, 2023). "Based on these observations, quantification of CEP135 in individual cells has recently been proposed as a screening approach for tracking centrosome abnormalities during tumor progression." (PMID 36435816, 2022). "The tumor biology was also determined to be affected by hsa-miR-26b through targeting CEP135." (PMID 36820950, 2023). "Two custom dPCR probes were designed to target two somatic mutations, one in the CEP135 gene (CEP135:c.3389C>T:p.S1130F) and the other in the CCNF gene (CCNF:c.541-31G>C), identified through whole-exome sequencing of the tumor and absent in genomic DNA." (PMID 39596073, 2024).
cancer (6 papers, 2016 to 2023). A tumor composed of atypical neoplastic, often pleomorphic cells that invade other tissues. "To study whether CEP135 expression could be used as a biomarker capable of stratifying cancer patients with different outcomes, we performed survival analysis for thirty-three cancer types from TCGA dataset." (PMID 36435816, 2022). "Besides CEP135, current work provides data for the rest of the top ten genes that significantly correlate with survival probability among thirty-three cancer types and could be used by researchers as indications for novel biomarker discovery and verification." (PMID 36435816, 2022). "On the basis of the median expression of CEP135, secondary analysis was performed on the dataset GSE12452, and cancer patients in the dataset were separated into two groups, high expression and low expression." (PMID 36820950, 2023). "In the present study, the smoking-related methylation changes to RUNX3, IL6R, PTAFR, and ANKRD11 (cardiovascular-related genes) and CEP135 and CDH23 (cancer-related genes) corresponded to increased gene expression." (PMID 26756918, 2016). "At the single nucleotide polymorphism (SNP) mutation level and transcriptional level, we found that MAP4, YWHAG, KSR2, SPAG9, and CEP250 gene-related loci are different in cancer and paracancer tissues, and MAP4, YWHAG, CEP135, and CEP250 differed significantly at the transcriptional level." (PMID 36705386, 2023).
CEP135 also shares sentences with these, for which no sentence is quoted: autosomal recessive primary microcephaly (3 papers); infection (2); anemia (1); asthenozoospermia (1); Bardet-Biedl syndrome (1); developmental delay (1); Leber congenital amaurosis (1); male infertility (1); myopathy (1); Primary microcephaly (1); primordial dwarfism (1); schizophrenia (1); urothelial bladder carcinoma (1).